ZNF75CP (zinc finger protein 75C, pseudogene)
Description:
May be involved in transcriptional regulation.
Synonyms: formerly ZNF75C
Gene: Transcribed processed pseudogene on chromosome 11 (78,384,208 to 78,385,739, forward strand). Ensembl gene ENSG00000288393.
Subcellular location: Nucleus